VWF (von Willebrand factor)
Diseases named in the same sentence as VWF in open-access papers (continued):
Sharing a sentence is not in itself a finding about the gene and the disease.
Von Willebrand disease (continued). "In particular, upon vascular damage, the vWF protein is exposed and binds to GPIbα, which is responsible for the initial platelet adhesion, as shown by the bleeding disorders Bernard Soulier syndrome and von Willebrand disease." (PMID 35518205, 2022). "Finally, polyP also increases the binding of VWF to platelets in samples from patients with type 2 and type 3 von Willebrand disease." (PMID 36430595, 2022). "Von Willebrand disease type 1 patients exhibit decreased plasma levels of VWF, but in some patients no causative mutation can be identified in the VWF gene itself." (PMID 34572000, 2021). "The aim was to provide a standardized complementary test in the diagnosis of VWD and, using the results of the VWF multimer analysis, to refine the laboratory diagnosis of von Willebrand disease and better classify patients with VWD into individual types and subtypes." (PMID 34829500, 2021). "In the epidemiologic data, it is shown that patients who suffered from von Willebrand disease with VWF activity of about 25%29, had approximately 40–60% fewer arterial thrombotic events, which is why we assumed that decreasing VWF activity to 20% or less is of therapeutic interest." (PMID 33542410, 2021). "Decreased levels or dysfunctional VWF collectively produce the disorder von Willebrand disease." (PMID 33600794, 2021). "Plasma VWF activity is significantly impaired in patients without any substantial loss of plasma VWF antigen level, thus exhibiting a typical sign of von Willebrand disease, although no associating mutation was found in the VWF gene." (PMID 34904569, 2021). "These newly defined shear stress-induced pathways could facilitate the identification of new targets that can regulate the production of both FVIII and vWF and thereby provide novel ways of treating HA and von Willebrand disease." (PMID 33732691, 2021). "von Willebrand disease (VWD) is the most common congenital bleeding disorder caused by quantitative (types 1 and 3) or qualitative (type 2) deficiency of von Willebrand factor (VWF), and its clinical manifestations include mild to severe mucocutaneous bleeding." (PMID 31793247, 2020). "Von Willebrand disease (VWD) caused by genetic mutations in the Von Willebrand factor (VWF) gene is the most common inherited hemostatic disorder and associated with over 560 mutations and 217 polymorphisms in VWF gene." (PMID 32443696, 2020). "Based on epidemiologic data from patients with von Willebrand disease which showed approximately 40–60% fewer arterial thrombotic events in patients with VWF activity of about 25%28, we assumed that decreasing VWF activity to 20% or less is of therapeutic interest." (PMID 32636459, 2020). "The addition of VWF replacement or ddAVP/desmopressin was thought to confer more risk than benefit because no laboratory defect in VWF (qualitative or quantitative) was found to support a diagnosis of von Willebrand disease (VWD)." (PMID 30581553, 2018). "Von Willebrand disease (VWD) is the most frequent inherited bleeding disorder and is caused by either a quantitative and/or qualitative defect of the multimeric glycoprotein vonWillebrand factor (VWF).[...]." (PMID 28926986, 2017). "Most, but not all patients with type 2B von Willebrand disease (VWD)—which features gain-of-function mutations in the A1 domain of von Willebrand factor (VWF)—have no circulating large VWF multimers." (PMID 28640903, 2017). "Von Willebrand disease patients who do not express VWF or who express the type 2N variant with impaired FVIII binding show decreased FVIII plasma levels of <10% of normal." (PMID 25905473, 2015). "Type 3 Von Willebrand disease is an autosomal recessive disease caused by the virtual absence of the von Willebrand factor (VWF)." (PMID 25635880, 2015). "Deficiencies in VWF expression can therefore reduce WPB numbers, as seen in von Willebrand disease." (PMID 24735118, 2014).
Von Willebrand disease (continued). "Although we did recommend screening for von Willebrand disease and hyperlipidemia among her first-degree relatives, such family screening was already advisable on the basis of her own prior history of low plasma von Willebrand factor and elevated plasma lipids." (PMID 24954083, 2014). "Von Willebrand factor, an acute phase response protein and vital in the hemostatic process, is under normal circumstances carefully regulated in the body since too little or malfunctional protein will lead to different forms of the well‐known bleeding disorder von Willebrand disease." (PMID 39760182, 2025). "Consequently, the VWF:RCo/VWF:Ag and VWF:CB/VWF:Ag ratios are <0.7, mirroring the pattern observed in type 2A von Willebrand disease (VWD), and could serve as routine screening tools to evaluate VWF function and identify the loss of VWF large multimers." (PMID 40918032, 2025). "Thus, screening tests for von Willebrand Disease showed a reduction in vWF parameters." (PMID 37569632, 2023). "VWF multimers are vulnerable to physiologic degradation by the action of a certain metalloprotease named ADAMTS13 (A Disintegrin-like And Metalloprotease domain with Thrombospondin type I motif), its susceptibility being increased for type 2A form of von Willebrand disease." (PMID 37241186, 2023). "Acquired von Willebrand disease (VWD) may result from elevated shear stress conditions and is characterized by the loss of high-molecular-weight multimers of the von Willebrand factor (VWF), leading to impaired VWF-mediated platelet functions." (PMID 33800006, 2021). "They include von-Willebrand disease, the most common inherited bleeding disorder in which patients lack functional, high molecular weight forms of VWF, and thrombotic thrombocytopenic purpura, which is characterized by vascular occlusions resulting from highly elevated VWF levels in the vasculature." (PMID 29899263, 2018). "Although clinical experience of a triple‐secured, plasma‐derived, von Willebrand factor (pdVWF), almost devoid of Factor VIII (FVIII) in adults with von Willebrand disease (VWD), is widely reported, its use in children is less documented." (PMID 41085048, 2025). "In our study, we explored how specific genetic changes in von Willebrand factor (VWF), a protein crucial for haemostsis, lead to a bleeding disorder called von Willebrand disease (VWD)." (PMID 41337046, 2025). "Von Willebrand disease (VWD) is one of the most common bleeding disorders, stemming from irregularities in the Von Willebrand factor (VWF)." (PMID 41322438, 2025). "The efficacy and safety of prophylaxis with wilate, a plasma-derived von Willebrand factor/factor VIII concentrate, was demonstrated in patients with von Willebrand disease of all types in the WIL-31 study." (PMID 41278463, 2025). "Gene therapy remains the only cure for von Willebrand disease (VWD), but it is limited by the large von Willebrand factor (VWF) gene size." (PMID 40958414, 2025). "Von Willebrand's disease (VWD), characterized by quantitatively or qualitatively abnormal von Willebrand factor (VWF), is the most common inherited bleeding disorder." (PMID 38690476, 2024). "In hereditary von Willebrand disease (VWD), treatment with recombinant or plasma-derived von Willebrand factor (rVWF or pVWF) is common practice." (PMID 36627675, 2023). "Wilate® is a 1:1 balanced mixture of von Willebrand factor and coagulation factor VIII registered in Switzerland for prophylaxis and treatment of bleeding in patients suffering from von Willebrand disease and haemophilia A." (PMID 36670471, 2023). "Up to one percent of the population suffers from von Willebrand disease (VWD), a usually autosomal dominant inherited quantitative or functional deficit of the factor VIII carrier protein, affecting the von Willebrand factor (VWF)." (PMID 35429255, 2022).
Von Willebrand disease (continued). "von Willebrand disease (VWD) is an inherited bleeding disorder characterized by quantitative and or qualitative defects in von Willebrand factor (VWF), a large multimeric protein, which plays a critical role in primary haemostasis." (PMID 36051064, 2022). "A 55-year-old male patient, known since childhood as having type 2 von Willebrand disease (vWD), with very mild symptoms, with one or even less annualized bleeding rate (ABR), was treated on-demand with FVIII containing vWF." (PMID 35743393, 2022). "Various hereditary types (type 1–3) of von Willebrand disease (VWD) are described, in which mainly a reduction of VWF and/or VWF-multimers is involved." (PMID 36452355, 2022). "Failure to produce correctly matured VWF and release it through regulated WPB exocytosis results in pathologies, most importantly von-Willebrand disease, the most common inherited blood clotting disorder." (PMID 34977047, 2021). "Von Willebrand factor (VWF) is a multimeric protein that is required for platelet adhesion and whose lack results in von Willebrand Disease (VWD), the most common coagulation disorder in humans." (PMID 31594977, 2019). "The complex between von Willebrand factor (VWF) and factor VIII (FVIII) is imperative for hemostasis, and failure to form this complex leads to bleeding diatheses such as hemophilia A and von Willebrand disease (VWD)." (PMID 31349985, 2019). "von Willebrand factor (VWF) level and function are influenced by genetic variation inVWFand several other genes in von Willebrand disease type 1 (VWD1) patients." (PMID 31249928, 2018). "The multimeric analysis (MA) of plasma von Willebrand factor (VWF) evaluates structural integrity and helps in the diagnosis of von Willebrand disease (VWD)." (PMID 29924855, 2018). "von Willebrand factor can interact with osteoprotegrin to regulate osteoclast differentiation, and a transgenic GP1BA von Willebrand disease model has increased bone mass and reduced osteoclast activity." (PMID 26023928, 2015). "Laboratory findings are similar to those of congenital von Willebrand disease (VWD), frequently with a prolonged bleeding time and low levels of von Willebrand factor measurements (VWFAg, functional assays and/or abnormal VWF multimers)." (PMID 25544909, 2014). "Previous studies have outlined the relationship of VWF level/activity and PFA-100 response, either in case of defective activity (Von Willebrand disease) or in case of hyperactivity (thrombotic disorders)." (PMID 24453831, 2013). "Von Willebrand disease (VWD) is an inherited hemorrhagic disturbance related to quantitative and/or qualitative defects of the von Willebrand factor (VWF)." (PMID 23970904, 2013). "In type 1 von Willebrand Disease (VWD) patients, von Willebrand Factor (VWF) levels and bleeding symptoms are highly variable." (PMID 22792389, 2012). "Prophylaxis with von Willebrand factor is recommended in people with severe von Willebrand disease (VWD), regardless of age." (PMID 40224272, 2025). "The 2021 ASH ISTH NHF WFH guidelines recommendation that patients with von Willebrand factor (VWF) levels of 30 to 50 IU/dL and an increased bleeding phenotype be categorized as type 1 von Willebrand disease (VWD) rather than Low VWF has proved controversial." (PMID 39265913, 2024). "For instance, the half-life of FVIII in the absence of vWF, as is the case in von Willebrand Disease, is around 3 h, while in the presence of vWF, FVIII half-life is 12 h." (PMID 33732691, 2021). "In addition, synthetic AVP (desmopressin) is used as procoagulant treatment, for example, in von Willebrand’s disease (vWD), as it increases platelet release of coagulation factor VIII and von Willebrand factor after administration." (PMID 34156969, 2021). "Another possible mechanism is an abnormality in von Willebrand Factor (VWF), although we did not observe an abnormal waveform in the single subject with von Willebrand disease who was examined in the present study." (PMID 33664450, 2021).
Von Willebrand disease (continued). "The centralised study ‘Molecular and Clinical Profile of von Willebrand Disease in Spain (PCM-EVW-ES)’ has been carried out by including the phenotypic assessment and the genetic analysis by next generation sequencing (NGS) of the VWF gene (VWF)." (PMID 29924855, 2018). "The importance of VWF for sustained levels of circulating FVIII is clearly demonstrated in patients with the severe type of von Willebrand disease (vWD), in whom no circulating VWF is detectable." (PMID 30873482, 2018). "However, clinical studies exploring levels of VWF in cancer patients, and specifically those with von Willebrand disease (VWD), have presented a picture that is more consistent with a pro-metastatic role for VWF." (PMID 28035064, 2017). "Further workup with coagulation studies showed decreased factor VIII, vWF antigen, and vWF:ristocetin cofactor assay, and negative Bethesda assay, indicating acquired von Willebrand disease." (PMID 29225984, 2017). "This is in contrast to the high shear stress encountered in the presence of a pulsatile LVAD or an aortic stenotic valve, which induce an acquired von Willebrand disease (AvWD), because the conformational changes of the HMWM-vWF resulted in excessive vWF cleavage and pathological bleedings." (PMID 27485105, 2016). "The critical importance of the interaction of VWF with GPIb-IX-V for hemostasis was shown in patients with Bernard Soulier syndrome (BSS) who lacked GPIb-IX-V or with patients with von Willebrand disease (VWD) who lacked VWF." (PMID 25297919, 2015). "von Willebrand disease type 3 (VWD3) is a rare but the most severe form of von Willebrand disease; it is due to almost complete lack of von Willebrand factor activity (VWF:RCo)." (PMID 25960895, 2015). "Platelet-type von Willebrand disease (Pt-VWD) also called pseudo-von Willebrand disease, is a gain-of-functions condition similar to VWD-type 2B characterized by spontaneous binding of plasma VWF to platelets and increased platelet agglutination with low amounts of ristocetin." (PMID 25297919, 2015). "Type 3 von Willebrand disease is a very rare inherited disorder characterized by a total lack of VWF synthesis and, thus, the absence of VWF from the vascular compartment (endothelial cells and subendothelium) as well as from MKs and platelets." (PMID 23737952, 2013). "Fourth, conditions possibly affecting sPsel and VWF levels in the enrolled patients, such as von Willebrand disease or congenital platelet function defects, were not excluded." (PMID 24034700, 2013). "Indeed a switch of B4galnt2 gene expression from intestine epithelial cells to vascular endothelial cells, resulting in aberrant VWF glysosylation, explained the phenotypic characteristics of the RIIIS/J mice similar to human type 1 von Willebrand disease." (PMID 24086150, 2013). "Similarly, platelet vWF has been shown to partially compensate for the lack of plasma vWF in pigs with severe von Willebrand disease." (PMID 36361561, 2022). "Hemophilia A (HA), hemophilia B (HB), and von Willebrand Disease (VWD) are the most common IBDs associated with a lack of clotting factors (blood coagulation factor VIII (F8), factor IX (F9), and von Willebrand factor (VWF), respectively)." (PMID 34828413, 2021). "Aggregation of platelets evoked by ristocetin is dependent on conformational changes of von Willebrand factor facilitating the protein interaction with GPIb-IX-V receptor and that is why, ristocetin-induced platelet aggregation (RIPA) test was used to a diagnosis of von Willebrand disease." (PMID 30842734, 2019). "A type 3 von Willebrand disease (VWD) index patient (IP) remains mutation-negative after completion of the conventional diagnostic analysis, including multiplex ligation-dependent probe amplification and sequencing of the promoter, exons, and flanking intronic regions of the VWF gene (VWF)." (PMID 35328514, 2022).
Von Willebrand disease (continued). "Desmopressin is the first-line treatment for type 1 von Willebrand disease.For those who do not respond, who have contraindication to desmopressin or need prolonged treatment, replacement therapy with FVIII/VWF concentrates is the mainstay of treatment." (PMID 40673199, 2025). "If VWF: Ag and VWF: Rco are low and anti-human factor VIII is negative, the diagnosis acquired is Von Willebrand disease." (PMID 36766524, 2023). "Though von Willebrand disease (VWD) is a common coagulation disorder, due to the complexity of the molecular analysis of von Willebrand factor gene (VWF), not many reports are available from this country." (PMID 24675615, 2014). "A tight, noncovalent complex between VWF and FVIII prolongs the half-life of FVIII in plasma, and failure to form this complex leads to rapid clearance of FVIII and bleeding diatheses such as hemophilia A and von Willebrand disease (VWD) type 2N." (PMID 31349985, 2019).